GREM1 (gremlin 1, DAN family BMP antagonist)
Diseases named in the same sentence as GREM1 in open-access papers (continued):
Sharing a sentence is not in itself a finding about the gene and the disease.
tumor (106 papers, 2004 to 2026). "Further research suggests that GREM1 is strongly linked to several signaling pathways that facilitate tumor cell invasion and metastasis." (PMID 40066442, 2025). "Correlation analyses indicate that GREM1 is significantly positively correlated with genes associated with tumor invasion and metastasis, including TWIST1 and PDGFRA." (PMID 40066442, 2025). "Further studies indicate that GREM1, as a key regulatory factor, enhances the supportive role of tumor-associated mesenchymal stem cells (T-MSCs) in tumor cell invasion and metastasis." (PMID 40066442, 2025). "In this work, lower stromal and tumoural GREM1 transcript numbers were significantly associated with distant tumour recurrence, supporting the role of GREM1 loss for metastatic seeding." (PMID 40826447, 2025). "In prostate cancer, GREM1 has been linked to lineage plasticity and therapeutic resistance, allowing tumor cells to evade the effects of targeted therapy." (PMID 40066442, 2025). "Fib-GREM1, which was enriched mainly in MI basal tumour samples, exhibited characteristics associated with inflammatory responses and epithelial-mesenchymal transition, which highlights its immunoregulatory functions." (PMID 41281745, 2025). "We observed that GREM1 is not only linked to tumor cell proliferation, migration, and EMT but also closely associated with immune cell infiltration within the TME." (PMID 40066442, 2025). "Grem1 positivity in the tumor microenvironment is broadly associated with poor prognosis, reduced survival, and enhanced metastatic potential (“Bad” GREM1)." (PMID 37615860, 2023). "The results indicated that the function of GREM1 was linked to stroma formation, suggesting a significant role in tumor microenvironment constitution." (PMID 36091126, 2022). "In CRC, high GREM1 protein expression has been associated with low tumor stage and extended survival." (PMID 35883579, 2022). "Representative gene GREM1 was highly expressed in the enCAFs of tumor tissues, which was a risk factor; Representative genes IFG1 were highly expressed in erCAF of paracanceroush tissues." (PMID 35910200, 2022). "NK, NKT, and DC were positively related to GREM1 expression, associated with tumor cell killing, but a recent study revealed the functional silence in the tumor microenvironment of PDAC and thus facilitated tumor progression." (PMID 36091126, 2022). "In comparison, increased levels of GREM1 mRNA (found in 6% of the tumor biopsies) are rarely caused by amplifications." (PMID 31694641, 2019). "Furthermore, patients with high GREM1 expression exhibited a significantly higher tumor mutation burden (TMB) than those with low expression (P=1.2e-06)." (PMID 40066442, 2025). "Risk of Drug Resistance: Long-term reliance on single-agent GREM1 inhibitors might prompt tumor cells to activate alternative signaling pathways to evade drug effects, ultimately leading to resistance." (PMID 40066442, 2025). "Gremlin 1 (GREM1) is implicated in tumor progression and poor prognosis in multiple cancers." (PMID 40066442, 2025). "Notably, one of the most highly upregulated secreted factor genes was GREM1 (encoding the BMP2/4/7 antagonist Gremlin1) which we have previously shown to play a role in MM tumour development in vivo." (PMID 40263435, 2025). "The mechanisms underlying the GREM1–CRC relationship are unclear but may be related to expression in the tumor microenvironment given GREM1 expression is lower in CRC tissue than in adjacent non-cancerous and normal tissue." (PMID 39846783, 2024). "Interestingly, the genetic loss of Grem1 in the tumor compartment reduced the abundance of myofibroblastic CAFs in the tumor microenvironment of their PDAC mouse model." (PMID 37615860, 2023). "Moreover, transcript levels of genes associated with CRC susceptibility loci (e.g., Grem1 and Bmp4) and tumor development and invasion (e.g., Wnt5a, Ereg, Mmp3, Mmp13, Timp1, Saa3, Ptgs2, and Acsl4) were elevated in IL-11+ fibroblasts." (PMID 33863879, 2021).
tumor (continued). "It has been reported that GREM1 is overexpressed in tumor-associated stromal cells." (PMID 33287358, 2020). "Because CD10 and CD34 are expressed by peritumoral stromal cells as well as tumor cells, we examined whether GREM1 has any associations with expression of stromal CD10 and CD34, and found a strong correlation of GREM1 expression with CD10 expression." (PMID 28346486, 2017). "Quantitative real-time PCR analysis of the same samples as used in the microarray analysis confirmed the marked downregulation of WIF1 in both neoplastic epithelium and tumor stroma and the marked upregulation of GREM1 in both DCIS-associated and IDC-associated stroma." (PMID 19187537, 2009). "Additionally, elevated GREM1 expression may be linked to genomic instability in tumor cells, potentially facilitating tumor invasion and metastasis." (PMID 40066442, 2025). "Previous research has demonstrated that GREM1 regulates tumor progression through the BMP and TGF-β signaling pathways." (PMID 40066442, 2025). "In pancreatic cancer, GREM1 plays a critical role in maintaining tumor cellular heterogeneity and therapy resistance, leading to increased tumor aggressiveness and poor prognosis." (PMID 40066442, 2025). "Recent studies have highlighted the pivotal roles of PLAU and GREM1 in modulating tumor treatment responses." (PMID 41048340, 2025). "In the TCGA-LUAD dataset, which includes 594 patient samples (535 tumor samples and 59 normal samples), GREM1 expression levels were significantly higher in tumor tissues compared to normal tissues (P<0.001)." (PMID 40066442, 2025). "This study systematically examines GREM1 expression in LUAD and its association with tumor progression, immune microenvironment, and prognosis." (PMID 40066442, 2025). "Together this provides accumulating evidence for a possible pleiotrophic role for GREM1 inhibition in neoplasia and requires further detailed study." (PMID 40467544, 2025). "GREM1 was found to promote tumor progression, and was identified as a mediator of the transition from NFs to CAFs by inhibiting the TGF-β pathway." (PMID 40069570, 2025). "Increased GREM1 levels can alter the composition of the tumor microenvironment, promoting the survival and proliferation of CSCs." (PMID 40277903, 2025). "In summary, mechanistic analysis shows that GREM1 plays a critical role in tumor invasion, metastasis, and immune evasion." (PMID 40066442, 2025). "Ectopic expression of SHH or FGF4 activated GREM1/FGF4/SHH signaling and rescued the anti-tumor effects of GREM1 knockdown in vivo." (PMID 40849639, 2025). "Given the high heterogeneity of LUAD and the complex tumor-immune interactions, a comprehensive analysis of GREM1 is warranted to elucidate its prognostic significance and immunoregulatory function." (PMID 40066442, 2025). "Conversely, GREM1 knockdown in H1650 cells significantly decreased proliferation (P<0.01), suggesting that GREM1 is crucial for tumor cell proliferation." (PMID 40066442, 2025). "Bioluminescence imaging documented that the knockdown of GREM1 in CAF-exo significantly reduced tumor growth." (PMID 40849639, 2025). "The development of these inhibitors primarily hinges on the critical role of GREM1 in tumor progression." (PMID 40066442, 2025). "PLAU was involved in angiogenesis, cell migration and invasion, and GREM1 was associated with the transforming growth factor (TGF)-beta signaling pathway, which was important for tumor progression and immune evasion." (PMID 41048340, 2025). "The results revealed significant differential expression of GREM1 related to tumor status (P=0.03) and staging (P=0.03), with significantly higher expression levels in stages T2 and T3." (PMID 40066442, 2025). "GREM1 modulates immune cell distribution and activity within tumors, impacting gene networks involved in tumor progression, immune evasion, cell proliferation, and migration, thereby playing a vital role in the TIME." (PMID 40066442, 2025).
tumor (continued). "These sample reports suggest intricate paracrine signaling loops where GREM1 and other proteins are secreted from MSCs and other cells, and act on differing cell types in the tumor microenvironment." (PMID 40277903, 2025). "An in vivo study using a mouse model of multiple myeloma demonstrated that an anti-GREM1 neutralizing antibody from UCB reduced tumor burden by up to 81.2%." (PMID 40277903, 2025). "In addition, a higher protein level of GREM1 in pancreatic ductal adenocarcinoma was linked to stroma formation and immunosuppression by recruiting immunosuppressive cells, including T regulatory cells, M2 macrophages, and exhausted T cells into the tumor microenvironment." (PMID 40849639, 2025). "To investigate the influence of GREM1 on macrophage polarization in tumor microenvironment, we transfected MC38 cells with lentivirus knocking down GREM1 or empty vector(MC38/sh-GREM1 or MC38/sh-NC)." (PMID 38970064, 2024). "FN1 was also an important gene in CTHRC1+GREM1+ myCAF, which has been shown to promote angiogenesis and metastasis of tumor cells through integrin signaling, leading to the activation of the FAK pathway and also contributing to EMT39." (PMID 39075108, 2024). "Further analysis revealed that EMT was an extremely significant mechanism regulated by CTHRC1+GREM1+ myCAF, indicating these fibroblasts support cancerous cell differentiation and proliferation leading to rapid tumor growth and potential metastasis." (PMID 39075108, 2024). "We found that miR-455 and BMP6 expression was increased and GREM1 expression was decreased in liver metastase compared with primary tumor." (PMID 38970064, 2024). "Further, we discovered that GREM1 was significantly increased in tumor tissues than in nearby healthy bladder tissues." (PMID 37605239, 2023). "We will then discuss the considerably fewer number of reports in which GREM1 is described to act as a tumor suppressor." (PMID 37615860, 2023). "These Grem1-positive EMT-tumor cells reduced Snail and Slug expression in neighbouring EpCAM + cells, thereby maintaining their epithelial state (“Good GREM1”)." (PMID 37615860, 2023). "A recent publication in Nature showed that in pancreatic adenocarcinoma (PDAC), the primary source of Grem1 expression is derived from tumor cells that have undergone epithelial-to-mesenchymal transition (EMT) and lost EpCAM expression." (PMID 37615860, 2023). "Meanwhile, Rbfox3 and SFRTM2 levels were downregulated while the levels of the fibrosis markers HGF, HMOX1, ELN, and GREM1 were upregulated in the tumor microenvironment of NEPC." (PMID 37240308, 2023). "Higher intra-tumoral expression of GREM1 in PDAC contributes to tumor stroma and immunosuppressive tumor microenvironment, presenting its therapeutic potential." (PMID 36091126, 2022). "The experimental results tell that knockout of Grem1 in PDAC cells leads to more de-differentiated tumours of mesenchymal-type, whereas over-expression of Grem1 leads to more differentiated tumours." (PMID 36224174, 2022). "There are sporadic reports of detailed insights into the molecular mechanisms of GREM1-mediated tumor-igenesis." (PMID 35883579, 2022). "GREM1 was found to be overexpressed in an array of common neoplasms of cervix, ovary, lung, stomach, breast and kidney, and to interact with YWHAH protein to exert a pro-carcinogenic effect." (PMID 35883579, 2022). "GREM-1 was reported to be the most consistently expressed gene at a higher level in basal cell carcinoma stromal cells compared with non-tumor skin." (PMID 35203511, 2022). "Taken together, GREM1 maintains the immunosuppressive tumor microenvironment, thus promoting PDAC progression." (PMID 36091126, 2022). "GREM1 was probably related to tumor growth, resulting from the positive correlation with tumor size (HR = 7.097, p = 0.032) and histopathological grades (HR = 2.898, p = 0.014)." (PMID 36091126, 2022).
tumor (continued). "Logistic analyses showed serum GREM1 positively correlated with tumor size (hazard ratio (HR) = 7.097, p = 0.032) and histopathological grades (HR = 2.898, p = 0.014)." (PMID 36091126, 2022). "PVT1 silencing reduced tumor migration and invasiveness via sponging miR-128-3p, which inhibited GREM1 and inhibition of the BMP signaling pathway." (PMID 34322395, 2021). "Studies reported that the secretion of GREM1 contribute to treatment resistance by maintaining cellular proliferation and cellular hierarchies within the tumor, and also increasing resistance to differentiation therapy." (PMID 33803224, 2021). "After the role of GREM1 in proliferation and invasiveness of transformed or cancerous human breast epithelial cell lines was confirmed, the effect of GREM1 on tumour formation in vivo was investigated in a xenograft mouse model." (PMID 32572171, 2020). "This was further supported in both the 5TGM1-KaLwRij and Vk*myc-C57BL/6 mouse models of MM, whereby significant increases in Grem1 expression were observed in the bones of tumor-bearing mice compared to normal controls." (PMID 32756430, 2020). "Cells with Grem1-knockdown showed much lower tumor growth rates and lung metastasis than control cells." (PMID 33287358, 2020). "Families with hereditary mixed polyposis syndrome have a germline 30 kb duplication on chromosome 15, upstream of the coding region of the GREM1 gene, but patients present with a colonic neoplastic disease phenotype." (PMID 32472605, 2020). "The findings show that overexpressed miR‐218 or silencing GREM1 led to the inhibition of tumour growth and liver metastasis of nude mice with OSCC." (PMID 33107676, 2020). "Most notably, targeting Grem1 with a neutralizing antibody significantly reduced MM tumor burden in the 5TGM1/KaLwRij.Hsd model of MM." (PMID 32756430, 2020). "Our studies showed that, compared to immunoglobulin G (IgG) control antibody-treated mice, mice treated with an anti-Grem1 neutralizing antibody had a decrease in MM tumor burden of up to 81.2% (p < 0.05, two-way ANOVA)." (PMID 32756430, 2020). "In the studies presented here, we demonstrated for the first time that the use of a Grem1-neutralizing antibody (UCB Pharma) in the 5TGM1/KaLwRij mouse model of MM resulted in a reduction of up to 81.2% in mean MM tumor burden." (PMID 32756430, 2020). "The results revealed a low expression of miR‐218 in OSCC tissues compared with that in adjacent normal tissues, while the expression of GREM1 was high in the tumour tissues (n = 65)." (PMID 33107676, 2020). "We further verified that GREM1 expression was confined to fibroblasts using in situ RNA hybridization on tumor tissues." (PMID 32381040, 2020). "The addition of the Il-6 neutralizing antibody abrogated the increase in stromal Grem1 expression when OP9 cells were cultured with 5TGM1 tumor cells (p < 0.05)." (PMID 32756430, 2020). "So far, many studies have shown that overexpression of GREM1 can induce fibrosis and tumor promotion through EMT signaling." (PMID 33287358, 2020). "Following two weeks of disease establishment, mice (n = 10/treatment group) were randomly assigned to two groups that displayed comparable tumor burden to receive treatment with either a neutralizing anti-Grem1 antibody or an IgG control antibody." (PMID 32756430, 2020). "We used this pipeline to quantitatively evaluate our qualitative observation that GREM1+ cells tend to be physically closer to tumor cells than other stromal cells." (PMID 32381040, 2020). "Analysis of human and mouse BM stromal samples by quantitative PCR showed that GREM1/Grem1 expression was significantly higher in the MM tumor-bearing cohorts compared to healthy controls (p < 0.05, Mann–Whitney test)." (PMID 32756430, 2020). "In this study, compact bone was isolated from healthy and MM tumor-bearing mice and analyzed for differences in Grem1 expression." (PMID 32756430, 2020).
tumor (continued). "Our findings are consistent with previous studies that report upregulation of Grem1 within the tumor microenvironment, demonstrating for the first time that Grem1 is upregulated in the BM stroma of MM patients." (PMID 32756430, 2020). "To examine the role of Grem1 in MM tumor establishment and growth in vivo, we utilized the well-characterized 5TGM1/KaLwRij preclinical mouse model of MM." (PMID 32756430, 2020). "Tumor volume didn’t differ notably among the miR-137 inhibitor + si-GREM1, blank and NC groups (p > 0.05)." (PMID 31143092, 2019). "The expression of the potential tumor suppressor miR-137, GREM1 and the TGF-β/smad pathway-related genes in tissues were determined." (PMID 31143092, 2019). "In this study, we show that GREM1 mRNA in tumor biopsies correlates with poor survival in ER-negative breast cancer patients." (PMID 31694641, 2019). "Of note, a poorer overall survival (OS) was also seen in the patients with the highest levels of GREM1 mRNA in tumor biopsies." (PMID 31694641, 2019). "Our data strongly supports an association of GREM1 mRNA expression with the CMS4 subtype of CRC and that fibroblasts are the most likely cell source of GREM1 in these tumours." (PMID 31384391, 2019). "A growing body of studies have reported the key functional relevance of GREM1 in neoplastic diseases, which was among the genes exhibiting the most significant differential expression." (PMID 31143092, 2019). "GREM1, primarily expressed by stromal cells, is a bone morphogenetic protein (BMP) antagonist implicated in tumor progression and EMT." (PMID 29503225, 2018). "In line with the in vitro studies, we found that Grem1 expression is downregulated in tumours from Ptch1Col1(het) mice compared with controls." (PMID 27492255, 2016). "Although Grem1 was strongly expressed in the tumour stroma of control mice, expression was significantly reduced in Ptch1ΔCol1 mice." (PMID 27492255, 2016). "GREM1 is another gene present in the CIMP signature and is associated with tumor cell proliferation." (PMID 26463173, 2015). "Appropriate datasets were identified using a search for tumor – normal comparisons of datasets containing probes targeting GREM1 (Gremlin)." (PMID 22870311, 2012). "Two transforming growth factor beta superfamily members (GREM1 and INHBA) are strongly induced in the tumor-associated stroma." (PMID 19187537, 2009). "Moreover, the expression of GREM1 in tumor tissues was significantly and positively correlated with the PD-L1 and CD206 expression." (PMID 40849639, 2025). "Similarly, in the LUAD dataset GSE31210, which comprised 246 patient samples (226 tumor samples and 20 normal samples), GREM1 expression was significantly higher in tumor tissues (P<0.001)." (PMID 40066442, 2025). "Additionally, a nomogram integrating GREM1 expression and tumor staging showed strong prognostic predictive ability." (PMID 40066442, 2025). "In the Transwell assay, GREM1 expression levels strongly correlated with cell migration and invasion capacities, suggesting that GREM1 may promote tumor metastasis by enhancing cell motility." (PMID 40066442, 2025). "As revealed by RT-qPCR, CAF-exo treatment enhanced expression of GREM1 and CD206 as well as reduced expression of CD8 in liver-infiltrating tumor tissues, whereas knocking down the expression of GREM1 in exosomes significantly attenuated CAF-exo-induced gene expression changes." (PMID 40849639, 2025). "GREM1 was significantly upregulated in tumor tissues and correlated with poor prognosis." (PMID 40066442, 2025). "GREM1 encodes gremlin 1, which is a signaling protein involved in several pathways relevant to CRC, including the transforming growth factor-β (TGF-β) pathway which has been implicated in tumor invasion and metastasis." (PMID 40951278, 2025). "Furthermore, we investigated the impact of BM‐MSCs with varying levels of GREM1 on tumor growth in vivo." (PMID 40285538, 2025). "Tumor progression promoted by CAF-exo was blocked by knocking down GREM1 in CAF-exo." (PMID 40849639, 2025).